CRP (C-reactive protein)
Diseases named in the same sentence as CRP in open-access papers (continued):
Sharing a sentence is not in itself a finding about the gene and the disease.
viral infections (continued). "The serum CRP concentrations (mean ± SD) of patients with bacterial infections (221.9 ± 65.2 mg/L) were significantly higher (P < 0.05) than those of the patients with viral infections (14.0 ± 13.8 mg/L) or of the controls (4.6 ± 7.0 mg/L)." (PMID 23690657, 2013). "It is possible that other types of patients (for example, solid organ transplant recipients, febrile neutropenia, allogeneic stem cell transplantation) as well as infections (for example, viral infections) may have different CRP time-courses." (PMID 21762483, 2011). "However, the specificity of CRP is relatively low, as it cannot distinguish between inflammation caused by viral infections and other infectious or non-infectious inflammatory states." (PMID 40444276, 2025). "Additionally, viral infections might interfere with the CRP levels induced by bacterial infections through immune system regulation." (PMID 40046054, 2025). "While CRP levels > 140 mg/L strongly predict bacterial co-infection or primary bacterial etiology, its behavior in early viral infections is nuanced: modest CRP elevation (typically < 50 mg/L) may indicate subclinical inflammation despite absent severe symptoms." (PMID 41308272, 2025). "However, other conditions, including viral infections and inflammatory conditions that may lead to mild elevations in CRP, usually reach up to 25 mg/L and 50 mg/L, respectively." (PMID 41156783, 2025). "Furthermore, equipping pharmacists with C-reactive protein kits can help distinguish between viral and bacterial infections, which may help reduce the inappropriate dispensing of antibiotics for viral infections like cold and flu." (PMID 40433488, 2025). "However, the results of this study revealed that CRP had limited effectiveness in differentiating between viral infections and viral-bacterial co-infections, while showing better performance in distinguishing bacterial infections from bacterial-viral co-infections." (PMID 40046054, 2025). "C-reactive protein appears to alter a larger APR in bacterial disease than in viral disease and as a result, CRP may be a candidate for guiding antibiotic initiation in pigs and evaluate treatment efficacy, though additional research is required to confirm this." (PMID 39237955, 2024). "Additionally, CRP was highly elevated in atypical pneumonia compared to viral infections." (PMID 39969364, 2024). "Importantly, CRP production is greater in response to bacterial as compared to viral infection." (PMID 38241274, 2024). "Moreover, there is a significant difference in the intermediate values of CRP (100–150 mg/L) between the eCRPv of patients with bacterial and viral infections for which the differential diagnosis is controversial, further demonstrating that a high eCRPv is indicative of a bacterial infection." (PMID 36477474, 2022). "Thus, cannabis could affect the immune system, could stimulate inflammatory cytokine production and CRP levels, and could decrease resistance to viral infections." (PMID 36733281, 2022). "However, in some viral infections, cytokine and C-reactive protein (CRP) levels might be quite high." (PMID 35547462, 2022). "In addition, viral infections rarely exhibit a substantial rise in CRP levels." (PMID 34945133, 2021). "In clinical medicine, measurements of the plasma concentration of CRP are used as a multipurpose marker that, depending on the cut-off level used, can be applied, among other tests, to screen for inflammatory diseases and to differentiate bacterial from viral infections." (PMID 35011944, 2021). "Furthermore, fever and elevated CRP in viral infections are common in this regard." (PMID 33425269, 2020). "Furthermore, CRP is a non- specific marker of inflammation and might be influenced by several conditions such as bacterial or viral infection, inflammatory diseases, connective tissue disorders, severe stress, and medical treatments." (PMID 33023215, 2020).
viral infections (continued). "Given recent evidence suggesting a role of infectious agents in ovarian cancer, a possible protective effect of CRP on endometrioid carcinoma could speculatively reflect the involvement of CRP in acute immune response (i.e., protection against active bacterial and viral infections)." (PMID 31390370, 2019). "The clinical presentation with a cough, wheezing, low-grade-fever, CRP below 50 mg/L and rhonchi on auscultation in 33% of the youngest children can also be considered as a childhood asthma-like exacerbation, primarily due to viral infection in pre-school children." (PMID 29698412, 2018). "The level of microRNA concentration is reversed to the ΔCT, so it is suggesting that this miR-150-5p is positively correlated with MAVS 70 kD and might facilitate anti-viral activity during viral infection and this might be reflected by elevation of CRP levels clinically." (PMID 30105262, 2018). "FebriDx provides qualitative results for elevated serum levels of c-reactive protein (CRP), an acute phase reactant associated with bacterial infection, and myxovirus resistance protein A (MxA), which is a derivative of interferonα/β associated with viral infection." (PMID 28991170, 2017). "Thus, the IL-18 response in viral infections is responsible for hyperferritinemia, while bacterial infections are characterized by an IL-1β/IL-6 response, culminating in elevated plasma levels of CRP." (PMID 27977798, 2016). "Use of CRP rapid tests in remote settings could help ensure that patients in need of antibacterial treatment are identified as such, while reducing unnecessary use of antimicrobials in viral infections." (PMID 26846919, 2016). "Biomarkers such as white blood cell (WBC) count, neutrophil cell count, C-reactive protein (CRP), procalcitonin and various cytokines have been suggested to be useful for quantifying the magnitude of inflammation or differentiating between bacterial and viral infection." (PMID 26034987, 2015). "However, similarly to studies in adults, suPAR was less accurate than CRP as diagnostic biomarker and also did not have any value in discriminating bacterial from viral infections." (PMID 24882949, 2014). "Quantitative CRP concentration in plasma or serum has been used as a screening tool for bacterial and viral infection; a range of 10–40 mg/L occurring in mild inflammation and viral infection, while a range of 40–200 mg/L is observed in active inflammation and bacterial infection." (PMID 24708690, 2014). "Thus, low CRP levels may suggest a viral infection and, depending upon the clinical and radiological findings, enables the suspension of antibiotic therapy and helps considerably in the reduction of the hospital stay." (PMID 22591236, 2012). "However, according to current findings and those reported in the literature, it may be concluded that the lower mean of age as well as the lower levels of CRP are characteristics found in viral infections of these cases in Belém city." (PMID 22591236, 2012). "Because this virus requires high concentrations of cytoribosomes in its host cell to undergo efficient translation, tightly controlled expression of CRP genes at levels just sufficient for normal growth and development may protect against viral infection and provide a selective advantage." (PMID 17927810, 2007). "Analysis of laboratory inflammatory markers showed that CRP and PCT concentrations, as well as neutrophil counts, were characteristic of a viral infection such as influenza." (PMID 41598308, 2026). "This study revealed significantly elevated levels of Complete Blood Count (CBC) parameters, particularly WBC and Neu, along with inflammatory biomarkers (CRP, SAA) in bacterial RTIs compared to viral infections and healthy controls." (PMID 41308272, 2025). "IFN-stimulated genes (ISGs), including CRP, IFIT1, LRG1, SLC1A1, and CDKN1A, were upregulated during HBoV1 infection, suggesting that viral infection elicited an antiviral response from the host cell." (PMID 39846742, 2025).
viral infections (continued). "Due to these limitations, interest has shifted toward alternative biomarkers such as procalcitonin (PCT) and C-reactive protein (CRP), which have shown promise in differentiating bacterial from viral infections." (PMID 41149698, 2025). "CRP levels acutely rise in bacterial infections and severe viral infections, while PLT can significantly decrease due to inflammation or coagulation consumption, leading to a higher CRP/PLT." (PMID 41413629, 2025). "Although CRP POCT is a valuable tool in diagnosing bacterial infections, its specificity is limited, as viral infections can also lead to elevated CRP levels." (PMID 40920832, 2025). "At the same time, compared with the healthy control group, the Neu, Mon, CRP, and SAA in the viral infection group showed moderate increases." (PMID 41308272, 2025). "All three neonates exhibited low inflammatory markers (CRP of <0.5 mg/dL and a normal PCT), likely reflecting viral infection." (PMID 40710034, 2025). "Laboratory investigations, especially complete blood counts, hypersensitive C-reactive protein (hs-CRP), and selected biochemical markers, play a pivotal role in differentiating bacterial and viral infections." (PMID 41367602, 2025). "Our findings show that German GPs mainly use CRP-POCTs in patients with clinical signs for RTI in order to determine the need for antibiotics and to differentiate between bacterial and viral infections." (PMID 39159989, 2025). "In conclusion, the two-transcript classifier model exhibited a good discrimination power, which was better than procalcitonin, CRP and ESR for discriminating bacterial from viral infection in UC-OI." (PMID 41050698, 2025). "Compared with the viral infection group and the healthy control group, the median levels of WBC, Neu, Mon, CRP, SAA, NLR, and MLR in the bacterial infection group were higher than those in the viral infection group and the healthy control group." (PMID 41308272, 2025). "The maximum levels of white blood cell count, absolute neutrophil count, and C-reactive protein differed between the groups, and the pairwise comparisons revealed higher levels in young infants with UTI compared to definite viral infection." (PMID 38732074, 2024). "C-reactive protein (CRP), a marker of inflammation, has a long history of use in hospitals as a means of differentiating bacterial from viral infections." (PMID 38184547, 2024). "During viral infection, medical textbooks also describe a decrease in WBC (white blood cell, WBC), an increase in lymphocytes, and a slight rise in CRP levels relative to baseline levels." (PMID 38306568, 2024). "In terms of viral infection, SAA level is significantly elevated, and CRP and PCT levels are slightly elevated." (PMID 39411281, 2024). "Conversely, BUN, CRP, PCT, PaCO2, and the proportion of viral infections were significantly higher than in the survival group (P < .05)." (PMID 39533637, 2024). "Current tests such as procalcitonin (PCT), C-reactive protein (CRP) alone or combined with TRAIL and IP-10 have limitations in accurately identifying bacterial or viral infections." (PMID 39003476, 2024). "Aptamers were used as the recognition element of proteins related to inflammation (C-reactive protein or CRP), viral infection (spike protein of the SARS-CoV-2 virus), and thrombotic diseases (thrombin)." (PMID 38793970, 2024). "The results of this study show that LMR and WBC × CRP are highly useful diagnostic markers for the identification and management of adult patients with influenza B. However, this investigation was conducted using a small sample size, and no comparisons to other viral infections were made." (PMID 38306568, 2024). "Many studies have shown that several biomarkers, such as simple blood count and serum biomarkers, including C-reactive protein (CRP) and procalcitonin (PCT), provide clues for differentiating between bacterial and viral infections." (PMID 37275364, 2023).
viral infections (continued). "The patient was suspected to have myopericarditis on account of acute decompensation after viral infection, moderately increased levels of immunoglobulin light chains and increased ESR, CRP and fibrinogen." (PMID 37510237, 2023). "Other indicators, such as CRP and PCT, in infected neonates were within the normal range, which was consistent with the typical characteristics of viral infection." (PMID 37565246, 2023). "Consistent with previous literature, our study suggests that conventional host biomarkers (WBC count, ANC, CRP, and PCT) provide clues for differentiating between bacterial and viral infections in children with CAP." (PMID 37275364, 2023). "Currently, bacterial and viral infections are mainly differentiated on the basis of WBC and CRP levels, which typically has sensitivity of 60% and specificity of 70%, resulting in a high rate of misdiagnosis." (PMID 36095013, 2022). "Collectively, NP in plasma should be a more sensitive biomarker for viral infection, including SARS-CoV-2, than CRP and IL-6." (PMID 35529699, 2022). "There are reports stating that PCT and CRP values in neonates are increased in certain perinatal situations and mode of delivery; however, decreased PCT values can be observed in viral infection." (PMID 36158418, 2022). "The level of C-reactive protein (CRP) in term infants was different between those with coinfection with bacteria and those with simple virus infection." (PMID 35897053, 2022). "Currently used biomarkers, such as white blood cell count (WBC), plasma C-reactive protein (CRP), and procalcitonin (PCT), have insufficient ability to differentiate between bacterial and viral infections (4, –, 11)." (PMID 35080443, 2022). "C-reactive protein (CRP) and procalcitonin, which are typically more elevated in blood during bacterial than viral infections, have been incorporated into RDTs." (PMID 36812544, 2022). "PCT and CRP have both been used as biomarkers to differentiate bacterial and viral infections in clinical settings Compared to PCT, CRP is a more extensively studied biomarker but is less specific to bacterial infections." (PMID 35149284, 2022). "Previous studies presented high concentrations of CRP, procalcitonin (PCT) and interleukin-6 (IL-6) in bacterial infections compared to viral infections." (PMID 36477474, 2022). "Other outstanding observations included the elevated CRP, ESR, and LDH in both groups, reflecting viral infections, inflammatory reactions and tissue damage." (PMID 33634148, 2021). "Of note, the median urinary levels of CRP (p < 0.001) and IP-10 (p < 0.001) were significantly higher in children with UTI vs. viral infection (healthy controls excluded)." (PMID 34966702, 2021). "Many patients with severe ARDS show massively increased levels of leukocytes, C-reactive protein (CRP), interleukin (IL)-6, and D-dimers in response to the viral infection." (PMID 34638691, 2021). "Thus, cell types known to leave the circulation due to interferon stimulation, such as T and NK cells, may recover as viral infection is controlled and interferon-dependent inflammation falls, independent of ongoing CRP-associated inflammation." (PMID 34051148, 2021). "Data of this comparative study clearly shows that the FCBI-index method is superior to CRP and PCT when distinguishing between bacterial and viral infections." (PMID 34844193, 2021). "When the CRP concentration was ≤ 22 mg/L, PCT ≤ 0.18 ng/mL and rhinorrhea data combined together, discrimination of a viral infection from a bacterial infection was further improved." (PMID 34583675, 2021). "CRP and NLR have been regarded as predictors of systemic inflammation, bacterial or viral infections and tissue injuries." (PMID 34282057, 2021). "In contrast to CRP, the biomarkers TRAIL and IP-10 showed increased protein levels in viral infections." (PMID 34079538, 2021).
viral infections (continued). "One example is the use of CRP, IP-10, and TRAIL, which were identified in a proteomic study based on their ability to differentiate bacterial and viral infections." (PMID 34905580, 2021). "The combined test of serum amyloid A (SAA), C reactive protein (CRP), and blood routine can improve the effectiveness of diagnosis and differential diagnosis of bacterial and viral infections." (PMID 32724668, 2020). "Our data offer an explanation to the modest CRP levels seen in viral infections and IFN-α driven autoimmunity and corroborate prior observations showing an IFN-α dependent downregulation of CRP." (PMID 33584722, 2020). "Though current clinical biomarkers are beneficial for CAP diagnosis, CRP, PCT, and eosinophil counts still have difficulty separating bacterial from viral infections or mild from severe cases." (PMID 31316955, 2019). "Levels of CRP and SAA have been reported to be significantly higher in some bacterial infections when compared to viral infections." (PMID 30774579, 2019). "Infection with bacteria correlated with MPO, protozoa with CRP, AGP and Ferritin, while viral infection with CRP." (PMID 31442248, 2019). "CRP and Complete Blood Count (CBC) are the initial preferred tests to distinguish between bacterial and viral infections." (PMID 30974881, 2019). "Recently, there has been increasing focus on biomarkers (i.e. C-reactive protein (CRP) and procalcitonin) in delineating bacterial from viral infections." (PMID 29852003, 2018). "This study demonstrated that low CRP and low WBC were significant predictors of a viral infection (mainly dengue, CRP≤37mg/L and WBC≤7.9x103/mm3 on CART analysis)." (PMID 29852003, 2018). "Receiver operating characteristic (ROC) curves were generated to visualise the performance of CRP and PCT in differentiating bacterial versus viral infections for specified cut-off values." (PMID 29852003, 2018). "WBC, CRP, and PCT are useful markers of bacterial sepsis compared with viral diseases and other inflammatory conditions." (PMID 28348452, 2017). "The rapid quantification of PCT and CRP on dual-QDs-labeled LFS is of great clinical value to distinguish inflammation, bacterial infection, or viral infection and to provide guidance for the use of antibiotics or other medicines." (PMID 27013227, 2016). "They found that CRP, TRAIL, and IP-10 were each independent biomarkers for discriminating bacterial from viral infections." (PMID 27486746, 2016). "This assay detects levels of CRP + IP-10 + TRAIL and the combination of biomarkers showed high sensitivity and specificity for identifying bacterial and viral infections (sensitivity 95%; specificity 91%)." (PMID 27486746, 2016). "Thyroiditis may occur after a viral infection (referred to as subacute or De Quervain thyroiditis), in which case the patient typically has a viral sore throat, the thyroid is tender, and inflammatory markers (erythrocyte sedimentation rate and C-reactive protein) are raised." (PMID 16363909, 2005). "Given the potential link between psoriasis and viral infection, and the significance of inflammatory markers like resistin, CRP, and CMIT in suggesting systemic inflammation, it is critical to explore the incidence of viral infection in psoriasis patients with elevated levels of these markers." (PMID 40724556, 2025). "The serum post-infection evolution of CRP and IL-6 levels showed no significant variation between clusters, which is consistent with the nonspecific response to viral infection or immune challenges in general." (PMID 40076968, 2025). "Inflammatory markers such as IL-6, PCT, and CRP were markedly higher in bacterial sepsis at ICU admission, consistent with prior studies demonstrating a more robust cytokine response in bacterial versus viral infections." (PMID 40733612, 2025).